IL1B (interleukin 1 beta)
Diseases named in the same sentence as IL1B in open-access papers (continued):
Sharing a sentence is not in itself a finding about the gene and the disease.
cancer (continued). "In a transgenic mouse model of inflammation-driven cancer, we have previously shown that macrophage S1PR1 signaling is crucial for lymphangiogenesis by activating the NLRP3 inflammasome and subsequent activation of IL-1β release." (PMID 31357710, 2019). "While activation of pyroptosis provides powerful ammunition against many types of cancers, other researchers have reported that the NLRP3 inflammasome and IL-1β pathway promote cancer progression in animal and human breast cancer models and asbestos-induced malignant mesothelioma." (PMID 31156630, 2019). "Evidence support DNA damage and stress induce sustained IL‐6 and IL1B production in PCa through P2Y11 receptor‐p38 MAPK‐NF‐κB signalling pathway, which may play an essential role in promoting cancer cells proliferation, survival, invasiveness and metastasis." (PMID 30592148, 2019). "Based on the observation that tumor failed to induce IL-1β elevation in C3H/HeJ mice, the authors proposed that cancer induced muscle wasting through TLR4-mediated systemic inflammatory." (PMID 31480237, 2019). "Elevated levels of inflammatory cytokines in a variety of tumors, e.g., IL-6, IL-1β, TGF-β and CXCL1, have shown positive correlations with radioresistance in cancer cells, whereas blocking the effects of these cytokines/chemokines can enhance sensitivity to RT." (PMID 31752313, 2019). "Among the commonly upregulated LD+ associated genes in GBM cells and patient tumors, we found several hypoxia-related, key effectors of angiogenesis, macrophage recruitment and stromal remodeling in cancer (e.g. VEGF-A, TGF-β1, IL1β, ADM, IGFB3, LOX, CA9, THBS1, PLODs, ID2)." (PMID 31174567, 2019). "Whilst there is no shortage of data supporting a role for IL-1β in tumorigenesis, there are relatively fewer studies directly examining IL-1α in cancer development and progression." (PMID 31231372, 2019). "In conclusion, we show that KRAS-mutant cancer cells use host IL-1β to sustain IKKα-mediated non-canonical NF-κB activity responsible for MPE development and primary drug resistance." (PMID 29445180, 2018). "Implicating IL-1β-mediated inflammation in cancer development raises the possibility that IRAK1, upstream of IL-1β, and with a role in the NF-κB pathway via TLR/IL-1R signaling, may represent a target for cancer prevention in patients known to be at high risk." (PMID 30279971, 2018). "Our work shows that IL-1β derived from inflammatory UC-MSCs induces the production of downstream cytokines CCL2, CXCL1, IL-6, and IL-8 in an autocrine manner, which promotes stem cell-like characteristics of cocultured cancer cells." (PMID 29670904, 2018). "Adipocytes co-cultured with cancer cells exhibit de-lipidation, decreased expression of adipocyte markers such as Ap2 and FABP4, increased expression of MMP11, and enhanced release of inflammation-promoting cytokines IL-6 and IL-1β." (PMID 30356678, 2018). "Furthermore, the cross-talk between MSCs and cancer cells relates to CDH1 (E-cadherin) and IL-1B levels." (PMID 29760166, 2018). "We therefore defined the species-conserved healing wound cytokines (HWCs) as SPP1, IL1B and IL6, and considered whether the expression levels of these genes might have prognostic value in human cancers." (PMID 30054470, 2018). "Unbiased analyses identified cancer-elaborated CXCL1/PPBP, potent myeloid cell chemoattractants that drive inflammation and metastasis via CXCR1/CXCR2 on host cells, as the transcriptional targets of IL-1β-fostered KRAS-IKKα addiction." (PMID 29445180, 2018). "We found that already at these early stages of progression, HER2+ cancer cells upregulated expression of Ccl2 but not Csf2, Csf1, Il1β, and Il6." (PMID 29295986, 2018). "Taken together, these data suggest that KRAS-mutant cancer cells respond to pleural IL-1β via IKKα-mediated non-canonical NF-κB activation." (PMID 29445180, 2018).
cancer (continued). "KRAS-mutant cancer cells are shown to respond to host provided IL-1β in the pleural space by increasing non-canonical IKKα-RelB pathway activity." (PMID 29445180, 2018). "Collectively, these data indicate that mutant KRAS induces non-canonical NF-κΒ signaling of cancer cells in unstimulated and IL-1β-stimulated conditions." (PMID 29445180, 2018). "The co-existence of mutant KRAS and elevated IKKα-mediated non-canonical NF-κB signaling in the cancer cell, relentlessly driven by host IL-1β, leads to two important consequences." (PMID 29445180, 2018). "In this study, we found that cancer cells could induce an M2-like macrophage characterized by up-regulation of CD163 and Arg1, and down-regulation of IL-1b and IL-6 through Nrf2 activation." (PMID 30180849, 2018). "Moreover, it has been observed that pro-inflammatory cytokines including IL1β and NLRP3 were significantly up-regulated in visceral adipose tissue versus subcutaneous adipose tissue in cancer patients." (PMID 30447690, 2018). "IL-1β is predominantly produced by activated macrophages and adipocytes in the TME, although cancer cells may contribute to increasing its levels." (PMID 30154786, 2018). "Although, there was no study about the association of IL-1β C-511 T and TNF-α G308A polymorphisms on ICC risk until now, the study on cytokines expression related cancer has been reported which acts as a diagnostic marker for cancer." (PMID 30139338, 2018). "IL-1β then primed IFN-gamma-producing CD8+ T cells, thus promoting the clearance of cancer cells." (PMID 29780380, 2018). "Here the mechanism of pleural IL-1β function in MPE promotion is elucidated: CCL2-attracted monocyte-released IL-1β fosters NF-κΒ activation of MPE-prone KRAS-mutant carcinomas by potentiating non-canonical NF-κB signaling via IKKα." (PMID 29445180, 2018). "In addition, IL-1β, produced mainly by activated NLRP3 inflammasome, can also increase tumorigenesis and promote the migration of cancer cells." (PMID 28938606, 2017). "The exact mechanism causing fatigue during and after cancer treatment is not clear, but it is suspected that pro-inflammatory cytokines, especially TNF-α and IL-1β play an important role." (PMID 28109186, 2017). "IL-1β, IL-4, TGF-β1a, and IL-10 mRNA levels were unaffected by cancer cell EVs." (PMID 28947958, 2017). "CagA but not IL-1β was found to induce cell invasion and formation of an aggressive phenotype related to cancers." (PMID 27525003, 2016). "In addition, GEN-27 remarkably suppressed IL-1β-mediated HCT116 cells proliferation, which confirmed the major role of IL-1β in promoting cancer cell growth." (PMID 27057094, 2016). "The conflict results indicated that COX-2/HIF1 is probably not the only cancer promoting pathway in downstream of IL-1β." (PMID 27811377, 2016). "Considering the compelling evidence regarding IL-1β-mediated regulation of HIF-1α, a key regulator of PFKP and the glycolysis pathway in cancer cells, we further dissected if the IL-1β-HIF-1α signaling cascade is involved in ABCB5-mediated regulation of glycolysis." (PMID 27560924, 2016). "Cancer cells, especially those with cancer stem-like cells (CSCs) activity, such as triple negative breast cancer cells (TNBCs), secret effector cytokines, including IFN-γ, TNF-α, and IL-1β that activate MSCs immunosuppressive role." (PMID 27493669, 2016).
cancer (continued). "Thus, we proceeded with the gene expression analysis of the NF-κBp65 pro-inflammatory target genes by qPCR, having found that IL-1β, TNF-α and MCP-1 expression were upregulated in cachectic cancer patients compared with controls." (PMID 26053616, 2015). "Decursin and decursinol angelate from A. gigas inhibit not only NO production and NO-induced inflammation by suppressing MMP-9, iNOS, IL-1β, and TNF-α expression but they also demonstrate anti-cancer effects by inhibiting cell proliferation and activating apoptosis." (PMID 26083119, 2015). "We propose a working hypothesis in which MSCs interact with cancer cells and the outcome of this dynamic interaction is dependent on the expression of CDH1/IL-1β by cancer cells." (PMID 26204886, 2015). "Our data demonstrate that CXCR2 contributes to IL-1β-mediated EGFR transactivation in OSCC and may provide an explanation for the oncogenic effect of CXCR2 in this cancer." (PMID 26462152, 2015). "The pro-inflammatory cytokines TNF-α and IL-1β are also involved in the regulation of CXCR4 in human astroglioma cells, suggesting that inflammation may promote cancer development via CXCR4." (PMID 26176534, 2015). "In addition, IL-1β induced the activation of extracellular signal regulated kinase (ERK) and ERK inhibition decreased the up-regulation of CXCR4 induced by IL-1β, suggesting the involvement of ERK signaling in cancer metastasis." (PMID 26176534, 2015). "For example, IL-1B secreted by activated macrophages has been shown to induce tumorigenic progression by increasing neovascu-larization, and TNF-alpha secreted by macrophages increased invasiveness of cancer cells via MMP-dependent mechanism." (PMID 27275223, 2015). "However, most studies into the mechanisms of inflammation-driven metastasis have focused on the induction of chemokine receptors, which can direct the movement of cancer cells, by inflammatory cytokines such as TNF-α, IL-1β and IL-6." (PMID 24789104, 2014). "In cancer patients, inflammatory changes indicate that IDO may be induced by soluble factors including IFNγ, TNF-α, IL-1β, soluble CD40 ligand (sCD40L) and CTLA-4 ligation to CD80/CD86 expressed by DC." (PMID 24147117, 2013). "However, the authors could not find an overall correlation between cancer and polymorphisms in the promoter region of the very potent gastric acid secretion inhibitor IL1β, except the finding of a reduced risk of cancer in IL1β-31C carriers in Asian populations." (PMID 27785255, 2013). "A recent study showed that, in the absence of exogenous stimuli, a number of human cancer cells spontaneously produce functional IL-1β, which leads to constitutive activation of the inflammasome." (PMID 23383347, 2013). "In addition, cancer associated fibroblasts, inflammatory cells (especially type-2 macrophages) and cytokines (e.g., IL-1β, TNF-α and IL-6) have been shown to affect the regulation of autophagy in cancer cells through induction of a metabolic stress." (PMID 22974323, 2012). "IL-1β has been reported to activate ERK1/2 in several cell types, including cancer cells." (PMID 23083134, 2012). "First, HMGB1 is acutely translocated and secreted by immune cells in response to TNF-α, IL-1β, or LPS stimulation, whereas cancer cells have no known stimuli for translocation and secretion." (PMID 22496788, 2012). "Our microarray analyses indicated that IL1B was downregulated following transfection of both HN5 and FaDu cells with miR-7, consistent with a potential regulatory pathway existing between these molecules in cancer." (PMID 23115635, 2012). "Interestingly, in undifferentiated cells, genes involved in cancer/inflammatory pathways such as CXCL12, IGFBP3, IL1B, and WNT5A were down-regulated by PCB-153, whereas they were up-regulated by AhR ligands." (PMID 22262711, 2012).
cancer (continued). "In this study, we attempted to determine the mechanism by which Z-360 mediates analgesic effects using a mouse model of cancer-induced pain and examining ephrin B-Eph B receptor signalling in DRGs, NMDA receptor NR2B subunit phosphorylation, and IL-1β production." (PMID 20979661, 2010). "To determine whether CCK contributed to the increased levels of IL-1β in the cancer-inoculated region, we examined the effect of sulfated CCK-8 injection on IL-1β production." (PMID 20979661, 2010). "IL-1β and HMGB1 may contribute to cancer growth and progression." (PMID 40422244, 2025). "Interestingly, IL-1β signaling, rather than TIB presence, was associated with advanced-stage cancer." (PMID 39801513, 2024). "Furthermore, the significant positive correlation in the co-expression of IL-1β and IL-1RN in READ suggests that both genes, although overexpressed in cancer, interact in an inflammatory cycle, as previously demonstrated, where a 1β/1RN axis regulates various aspects of CRC via autophagy." (PMID 39766795, 2024). "In cancer, the corresponding signal transduction after PRR stimulation amplifies the effect of the immunosuppressive response of MDSCs by producing a variety of proteins, including arginase-1, iNOS, IDO-1, prostaglandin E2, PD-L1, CD40, TNF-α, IL-1β, IL-6, cyclooxygenase-2, and others." (PMID 39035356, 2024). "The relationship between inflammation and muscle density has been reported in non-cancer populations, and attempts to define the mechanistic pathways suggest that cytokines such as TNF, IL-6, and IL-1β may stimulate proteolysis and inhibit anabolism, leading to muscle breakdown and wasting." (PMID 38512880, 2024). "Notably, Tet2-KO HSCs relative to WT enriched for transcriptional signatures of cancer, myelopoiesis, and dysregulation of lymphopoiesis and hemopoiesis upon IL1β stimulation but not in steady state." (PMID 38062031, 2023). "In the first scenario, MDI (which consisted of a total dose of 10 Gy in five daily fractions) led to reduced mRNA expression of some proinflammatory markers (such as CCR7 and IL1β), with no changes documented for anti-inflammatory markers, while cancer cell invasion and migration were promoted." (PMID 37347290, 2023). "The levels of TNFα, IL-1β, IL-6, and IL-12 were not affected by the cancer cell spheroids." (PMID 37445941, 2023). "At the early stage of Omicron infection, IL-1β trended to decrease in both cancer patients and non-cancer-afflicted subjects; at the late stage, it remained at a low level without apparent fluctuation in cancer patients but trended to a marked increase in non-cancer-afflicted subjects." (PMID 37035158, 2023). "The role of IL-1β in cancer has both positive and negative functions and may be dependent on the cancer type and stage." (PMID 37449203, 2023). "M2 macrophages cultured without activation factors (w/o) after interaction with cancer cell spheroids had increased IL-1β (from (w/o) M2 90 pg/mL to S + (w/o) M2 136 pg/mL, p = 0.0009), IFNβ (from 0 to 0.6 ng/mL, p = 0.0300), and TNFα (from 98 to 131 pg/mL, p = 0.0007) cytokine secretion." (PMID 37445941, 2023). "Consequently, treatment of cells with the anti-cancer drug and DPP8/9 active site inhibitor talabostat (Val-boroPro, PT-100) induces NLRP1 activation in human keratinocytes and the downstream secretion of high levels of IL-1β." (PMID 36293159, 2022). "We hypothesized that the SIRPγhi CSLCs may regulate CD47 expression in CSLCs and bulk cancer cell population through autocrine or paracrine signaling, particularly as previous studies revealed that cytokines such as TNF-α and IL-1β can stimulate CD47 expression." (PMID 35229723, 2022). "In addition to Kras, Ccl2, and Il1b, a battery of other transcripts originated within the signature of KRAS-mutant cancers derived from the transcriptomes of our cell lines, providing synthetic lethality candidates for in vivo KRAS dependency for future research." (PMID 35327394, 2022).
cancer (continued). "While other TAB partners of TAK1, namely TAB2 or TAB3, may be involved in the regulation of TAK1 activity in other chronic conditions such as cancer, our focus remains on TAK1/TAB1 complex given its established role in IL-1β-induced TAK1 activation in human RASFs." (PMID 36032089, 2022). "In one study, a water JCo extract inactivated the PI3K–Akt pathway in cancer cells, and our data revealed that JCo extract suppressed NFκB expression and the downstream expression of chemokines and cytokines such as TNF‐α, IL‐1β, IL‐6, and CCL2 in the rat renal cell line NRK‐52E." (PMID 36249972, 2022). "Compared to HCV-infected patients with HBV reactivation, non-HCV infected patients with HBV reactivation who were treated with immunosuppressive agents/anti-cancer drugs or underwent BMT had significantly higher IL-1β levels than did those without HBV reactivation." (PMID 36207368, 2022). "Since IL-1β, TNF-α, and IFN-γ cytokines are believed to mediate cytotoxicity of IL-2 based immunotherapies, mutant IL-2 with reduced binding to the high-affinity IL-2R may be more effective and less toxic for cancer treatment." (PMID 35354847, 2022). "Thus, we comprehensively measured representative inflammatory mediators, including IL-1β, IL-6, IL-10, IL-12p70, TNF, PGE2, and VEGF concentrations in the saliva of patients with cancer, which is convenient to measure, less invasive to collect, and can be done repeatedly." (PMID 35476641, 2022). "As a common effector of TLR4 and inflammatory cytokine receptors that promote muscle wasting including TNFα, IL-6, IL-1β and members of the TGFβ superfamily including TGFβ and activin A/myostatin, p38β MAPK plays a central role in mediating muscle wasting in murine models of cancer." (PMID 34950660, 2021). "In GBM cell lines U-251 and U-87, the interaction of Ras (an oncogene) with TNFα/IL-1β was found to increase hypersecretion of IL-6/IL-8 cytokines and activation of the p38 MAPK signaling pathway, leading to the creation of an inflammatory microenvironment conducive for cancer progression." (PMID 34439380, 2021). "In Pt.3, with a shorter survival, we observed during treatment a decrease in nonclassical monocytes, which contribute to cancer immunosurveillance through NK cell recruitment and activation and are the primary producers of the inflammatory cytokines IL-1β and tumor necrosis factor-α (TNF-α)." (PMID 33430142, 2021). "Based on observations that IL-1β and IL-18 can contribute to AML anti-cancer drug resistance, and based on our data showing enhanced expression of PELI2 gene, mediating IL-1β and IL-18 activation may be a distinct plausible important mechanism by which PELI2 involved in emergence of drug resistance." (PMID 34127725, 2021). "However, in human non-cancer colon fibroblast cells, GAE promoted anti-inflammatory activities, which was accompanied by the reduction of intracellular ROS and the inhibited expression of TNF-α, IL-1β, IL-6, and NF-κB." (PMID 33664749, 2021). "It is possible that RF-FLS has already gained high mobility during a cancer-like transformation and the additional activation by IL-1β treatment might further not increase cell mobility." (PMID 34225810, 2021). "Their results suggest that surgical and metabolic response to an IA justify the adoption of an entirely laparoscopic approach performing a right colectomy for cancer, but the role of other inflammatory mediators, such as IL-1β, IL-10, IL-13, TNFα and insulin, was not considered." (PMID 33958669, 2021). "The inhibitory effects of IL1β and the positive correlation of IL1R1 levels with AR activities in LNCaP, but not C4-2 cells, suggested an interplay between the inflammation and androgen signals in maintaining the homeostasis of androgen-sensitive prostate tissues and cancers." (PMID 33322099, 2020).